AXL (AXL receptor tyrosine kinase)
Diseases named in the same sentence as AXL in open-access papers (continued):
Sharing a sentence is not in itself a finding about the gene and the disease.
viral infection (continued). "Some studies have identified the tyrosine-protein kinase receptor UFO (AXL) as a potential co-receptor, due to its specific interaction with the N-terminal domain of the SARS-CoV-2 S protein, which may enhance viral infection." (PMID 41472297, 2025). "AXL expression is not limited to DCs and macrophages—it is also detected on mature NK cells during viral infection and non-hematopoietic cells." (PMID 27350258, 2016). "The role of AXL in SARS-CoV-2 entry was established in three independent approaches: knocking down AXL in ACE2-negative AXL-high cells, which blocked infection; using soluble AXL to inhibit viral infection, and introducing AXL to AXL-negative HEK293T cells which enabled infection." (PMID 36423144, 2022). "However, soluble human ACE2 failed to block viral infection in cells overexpressing AXL, and vice versa, indicating that AXL’s function in mediating viral entry is likely independent of ACE2." (PMID 33420426, 2021). "These and other studies suggested that some drugs that block AXL might be useful treatments for viral infections, however it was not clear if this was the case for all viruses." (PMID 27350258, 2016). "It is clear that AXL is a new receptor of SARS-CoV-2 and can independently mediate viral infection of the human respiratory system without relying on ACE2." (PMID 37645223, 2023). "Knocking out of AXL, but not ACE2, greatly reduced viral infection in H1299 cells." (PMID 33420426, 2021). "Compared with those overexpressing human AXL, cells overexpressing murine AXL or rhesus macaque AXL showed greatly reduced SARS-CoV-2 virus pseudotype infection percentages, indicating that AXL may not facilitate viral infection in these animal models." (PMID 33420426, 2021). "Therefore, AXL and MER could redundantly facilitate viral replication by dampening the cellular innate antiviral response, rather than mediating viral infection by serving as receptors." (PMID 32695074, 2020).
acute myeloid leukemia (40 papers, 2011 to 2025). Acute myeloid leukemia (AML) is a group of neoplasms arising from precursor cells committed to the myeloid cell-line differentiation. "BGB324 (R428) is a selective AXL inhibitor and has been used for phase I studies in patients with refractory/relapsed acute myeloid leukemia (AML) and high-risk myelodysplastic syndromes." (PMID 29930762, 2018). "AXL has been also shown to be induced by chemotherapy drugs in acute myeloid leukemia and AXL is consistently associated to drug-mediated resistance in several types of cancer." (PMID 22141136, 2011). "For example, BGB324, a small molecule inhibitor of AXL, has entered phase I/II clinical trials for acute myeloid leukemia and pancreatic cancer." (PMID 37475048, 2023). "Overexpression of AXL has also been reported in several types of sarcomas, in acute myeloid leukemia (AML), and other hematologic malignancies." (PMID 35572601, 2022). "Bemcentinib is a newly developed AXL inhibitor that is currently under investigation in phase II trails for the treatment of acute myeloblastic leukemia (AML)." (PMID 32440898, 2020). "We present a male 81-year-old patient with a manifestation of alveolar bone necrosis at the central upper incisors following a 2-month regimen with the AXL-inhibitor Bemcentinib, administered for the treatment of secondary acute myeloblastic leukemia (sAML)." (PMID 32440898, 2020). "AXL expression has been found to be induced by chemotherapy drugs in U937 acute myeloid leukemia cells." (PMID 27172793, 2016). "AXL was found to be an independent prognostic marker and therapeutic target in acute myeloid leukemia (AML)." (PMID 25337673, 2014). "Notably, the drug gilteritinib, which targets AXL, has received approval for the treatment of acute myeloid leukemia, while AXL1717 is being investigation for NSCLC." (PMID 41463415, 2025). "Most research and clinical evidence has been provided for AXL inhibitors in acute myeloid leukemia." (PMID 31694201, 2019). "Further investigation is required to optimize this triple combination, however, these results suggest that AXL is a potential marker of response to Decitabine-Vorinostat combination treatment and offers a new avenue of epigenetic combination therapies for acute myeloid leukemia." (PMID 28881658, 2017). "Rationale: AXL expression has been identified as a prognostic factor in acute myeloid leukemia (AML) and is detectable in approximately 50% of AML patients." (PMID 38773967, 2024). "And finally, in acute myeloid leukemia (AML), methylation of the AXL promoter was inversely correlated with response to chemotherapy drugs." (PMID 32148495, 2020). "In addition, AXL has been shown to be induced by chemotherapy drugs in acute myeloid leukemia." (PMID 22141136, 2011). "Bencentinib, another AXL inhibitor supports the antiviral activity seen for gilteritinib, an FDA-approved drug for treating acute myeloid leukemia." (PMID 38827795, 2024). "Under serum starvation conditions, acute myeloid leukemia (AML) Nomo-1 and Kasumi-1 cells with Gas6 and AXL silenced with two distinct shRNAs showed a two- to three-fold increase in apoptosis." (PMID 37265798, 2023). "In 2013, the first AXL inhibitor, BGB324, entered clinical trials and is currently in Phase 1b clinical trials as a single agent and in combination with cytarabine in acute myeloid leukemia." (PMID 27834845, 2016). "As a member of the TAM receptor family (TYRO3, AXL, MERTK), MERTK is overexpressed in many solid cancers (such as breast cancer, colorectal cancer, and melanoma) as well as in hematological malignancies such as acute myeloid leukemia (AML)." (PMID 34835225, 2021). "AXL expression levels also negatively correlated with RIPK3 expression in stomach adenocarcinoma tumors and acute myeloid leukemia, based on the analysis of the Cancer Genome Atlas (TCGA) database using cBio Cancer Genomics Portal and according to both Pearson and Spearman correlation analyses." (PMID 30157175, 2018).
acute myeloid leukemia (continued). "In acute myeloid leukemia (AML), ALKBH5 was positively regulated by KDM4C and the high level of ALKBH5 increased the stability of AXL (AXL receptor tyrosine kinase), thus promoting leukemia stem cells." (PMID 36686788, 2022). "In acute myeloid leukemia (AML), ALKBH5 was required to maintain leukemia stem cell self-renewal and promote AML tumorigenesis by regulating the expression of a set of critical genes (AXL and TACC3) at the posttranscriptional level." (PMID 34759347, 2022). "For instance, ALKBH5 was reported to show highly expression in acute myeloid leukemia (AML) and to regulate the stability of AXL mRNA to maintain leukemia stem cell (LSC) function, nonetheless, recent reports have shown that ALKBH5 plays an inhibitory role in pancreatic cancer." (PMID 35114989, 2022).
pancreatic cancer (40 papers, 2014 to 2026). "We demonstrated that GAS6-CAR-T cells can inhibit the growth of pancreatic cancer PDX models by elimination of both AXL-positive tumor cells and tumor-associated macrophages." (PMID 37475048, 2023). "AXL inhibition in the Kras/cdKn2a mutated model (KIC) of pancreatic cancer was accompanied by a reduction in IL-7, CCL11, IL6, and IL-1ß levels, as well as a net reduction in F4/80+ tumor-associated macrophages expressing ARG1, a potent immunosuppressive enzyme." (PMID 35572601, 2022). "In pancreatic ductal adenocarcinoma, the upregulation of AXL has been associated with a poor clinical prognosis and increased cell proliferation, while stable knockdown of AXL resulted in a significant reduction in cell viability and anchorage-independent growth in pancreatic cancer cells." (PMID 37469409, 2023). "In animal models of pancreatic cancer, genetic deletion of AXL resulted in an enriched immune microenvironment and prolonged survival." (PMID 41560781, 2026). "AcRIP-qPCR and mRNA stability assays confirmed that NAT10 boosts AXL mRNA stability in an ac4C-dependent manner, resulting in elevated AXL expression, which in turn promotes the proliferation and metastasis of pancreatic cancer cells." (PMID 40881352, 2025). "In pancreatic cancer, RNA-seq screening identified the receptor tyrosine kinase AXL as a downstream target of NAT10." (PMID 40881352, 2025). "Antitumor activity was assessed through in vitro co-cultures with AXL-positive lung and pancreatic cancer cells, measuring cytotoxicity, cytokine secretion, and specificity." (PMID 40299452, 2025). "This is also the first study of the effect of NPS-1034, a dual inhibitor of MET and AXL, on pancreatic cancer." (PMID 39000029, 2024). "MET and AXL are important regulators of pancreatic cancer because they are receptor tyrosine kinases (RTKs) that function normally in healthy conditions." (PMID 39000029, 2024). "Future experiments should investigate if targeting AXL and other cell surface receptors can inhibit pancreatic cancer progression." (PMID 38920688, 2024). "Elevated NAT10 expression in pancreatic ductal adenocarcinoma (PDAC) increases the stability and enhances the expression of AXL mRNA through ac4C modification, thereby promoting pancreatic cancer progression." (PMID 39640362, 2024). "AXL induced TANK binding kinase 1 (TBK1)-NF-κB signaling pathway and innate immune suppression in the TME in pancreatic cancer, while inhibition of AXL with small molecule R428 enhanced immune stimulatory microenvironment." (PMID 37469409, 2023). "The receptor tyrosine kinases TAM family (TYRO3, AXL, and MERTK) are highly expressed in multiple forms of cancer cells and tumor-associated macrophages and promote the development of cancers including pancreatic tumor." (PMID 37475048, 2023). "Stable knockdown of endogenous AXL in pancreatic cancer cells resulted in a significant decrease of mRNA levels of matrix metalloproteinase (MMP)-9 and EMT-associated transcription factors twist, snail, and slug." (PMID 37469409, 2023). "BGB324 (BerGenBio); also known as R428 (Rigel Pharmaceuticals), is an oral selective small molecule AXL inhibitor that is currently being investigated in phase II clinical trials of pancreatic neoplasms." (PMID 37469409, 2023). "The role of AXL signaling in progression and metastasis of pancreatic cancer was confirmed in a study using low-dose warfarin, a vitamin K “antagonist” to inhibit Gas6-dependent AXL activation." (PMID 37469409, 2023). "Treatment with low-dose warfarin reduced AXL-mediated human pancreatic cancer cells migration, invasiveness, and proliferation, while increasing apoptosis and sensitivity to chemotherapy." (PMID 37469409, 2023). "Another study in phase I is assessing the use of warfarin in pancreatic cancer patients due to its effects on AXL pathways, which are found to have great implications in metastasis of pancreatic cancer." (PMID 35740545, 2022).
pancreatic cancer (continued). "By contrast, high AXL expression has a tread to be an independent poor prognostic marker in pancreatic cancer." (PMID 34778091, 2021). "Previous studies have also confirmed that AXL is critical in the progression and metastasis of pancreatic cancer." (PMID 34778091, 2021). "Activation of the tyrosine kinase receptor AXL and expression of its ligand growth arrest-specific protein 6 (Gas6) correlate with a poor prognosis and increased metastasis in pancreatic cancer patients." (PMID 32174917, 2020). "A similar RTK distribution has already been reported for TYRO3 and AXL in human colorectal cancer and pancreatic cancer, respectively." (PMID 30765874, 2019). "Chemotherapy combined with Gas6/AXL targeted therapy may provide new hope for metastatic pancreatic cancer." (PMID 40538442, 2025). "Indeed, chemotherapy has been reported to increase the infiltration of neutrophils in pancreatic cancer and results in metastasis via Gas6/AXL signaling." (PMID 38654356, 2024). "Thus, the immunohistochemical assessment of 99 pancreatic cancer specimens revealed a higher number of lymph node metastases and a shorter median survival of patients with AXL-positive tumors (12 versus 18 months) in contrast to the AXL-negative group." (PMID 37469409, 2023). "Several studies suggested AXL as a potential therapeutic target in pancreatic cancer." (PMID 37469409, 2023). "In the study of Ireland and colleagues, the blockade of GAS6 using warfarin in pancreatic models further revealed that inhibition of the GAS6/AXL axis could reduce cancer cell plasticity, activate NK cells and inhibit pancreatic cancer metastasis." (PMID 35572601, 2022). "Therefore, we choose the pancreatic cancer patient-derived xenograft (PDX) models with the high expression of AXL in both cancer cell and macrophage to test whether GAS6-CAR-T cells can also eliminate cancer cells and macrophages in vivo." (PMID 37475048, 2023). "Hence, our data reveal an additional novel role of AXL signalling in promoting the regrowth of cancer cells after chemotherapy in established distant lesions, thereby expanding the potential use of AXL inhibitors to fight pancreatic cancer." (PMID 35022267, 2022). "Hence, the dual inhibition of MET and AXL could be promising for pancreatic cancer treatment." (PMID 39000029, 2024). "The patient-derived pancreatic tumor tissue was chosen according to the expression of markers of tumor cells (CK19) and macrophages (CD68), and AXL detected by immunofluorescence." (PMID 37475048, 2023). "We found that AXL and MIG6 were coexpressed in many cancers, including pancreatic cancer, prostate cancer and sarcoma." (PMID 37834326, 2023). "AXL signalling may directly stimulate EMT in breast, ovarian and pancreatic cancer by activating EMT-TFs SNAIL, SLUG and TWIST; AXL transcription is, in turn, controlled by an EMT-TF ZEB1." (PMID 40044635, 2025). "Consistent with previous studies, AXL and TIMD4 increased in patients with pancreatic cancer." (PMID 34778091, 2021). "However, AXL and MERTK were up‐regulated in renal clear cell carcinoma and pancreatic cancer." (PMID 40576208, 2025). "However, despite the important roles that MET and AXL play in the progression of pancreatic cancer, there has been no research on NPS-1034 and pancreatic cancer." (PMID 39000029, 2024).
colorectal cancer (36 papers, 2014 to 2025). A primary or metastatic malignant neoplasm that affects the colon or rectum. "MZF1 activation has been implicated in the progression of cervical and colorectal cancer, where it increases invasion and metastasis, at least partially, via increased expression and activity of receptor tyrosine kinase AXL." (PMID 31963147, 2020). "Functional studies have shown that AXL inhibition by gene silencing or pharmacologic agents like foretinib can suppress proliferation, migration, and survival in colorectal cancer cells." (PMID 41515404, 2025). "GALNT2 has been shown to contribute to the enhanced aggressiveness of colorectal cancer cells, doing so in part by modulating the AXL pathway." (PMID 38596689, 2024). "In colorectal cancer, increased AXL contributes to the upregulation of TWIST1, which is directly related to EMT and mediates resistance to PLK1 inhibitors." (PMID 37328828, 2023). "In colorectal cancers, AXL induces the expression of Twist family BHLH transcription factor 1 (TWIST1) and mediates resistance to polo-like kinase 1 (PLK1) inhibitor." (PMID 37328828, 2023). "We, therefore, proposed that GALNT2‐mediated invasiveness of colorectal cancer is at least partly through AXL." (PMID 36409270, 2023). "Among the TAM receptors, AXL was consistently reported to play a crucial role in the invasive behavior of cancers, including colorectal cancer." (PMID 36409270, 2023). "TEAD combines with AXL promoter to enhance its promoter activity, in turn mediating the resistance of colorectal cancer to 5-FU." (PMID 37328828, 2023). "AXL was upregulated in 76% of patients with colorectal cancer and strongly correlated with a mesenchymal phenotype, whereas 37% of TGFBR2high and 65% of tumors TGFBR1high were attributed to the CMS4 subtype." (PMID 33570712, 2021). "The authors concluded from their results that the inhibition of AXL can represent a new therapeutic approach for colorectal cancer." (PMID 33759958, 2021). "Another study including 18 cases of CRC with subsequent silencing of AXL in a panel of colorectal cancer cell lines showed a statistically significant correlation between AXL expression and stage IV cancers in comparison to stage 0." (PMID 33759958, 2021). "Here, we report that XIST promotes colorectal cancer tumorigenesis by regulating miR‐93‐5p/HIF‐1A/AXL signaling pathway." (PMID 32061057, 2020). "In the present research, in order to determine if XIST modulates the activities of colorectal cancer by HIF‐1A/AXL signaling, the expression of AXL after loss‐ and gain‐of‐function of XIST was detected in colorectal cancer cells." (PMID 32061057, 2020). "Previous research has shown that HIF‐1 is capable of directly binding to AXL and activating the expression of it; therefore, to further study the mechanisms of XIST, the expression level of AXL in colorectal cancer cells was detected." (PMID 32061057, 2020). "XIST is a ceRNA for miR‐93‐5p to promote the progression of colorectal cancer partly through HIF‐1A/AXL signaling." (PMID 32061057, 2020). "At last, we proved that XIST enhanced the in vivo and in vitro activities of colorectal cancer by regulating AXL signaling." (PMID 32061057, 2020). "In colorectal cancer, AXL expression is associated to increased invasiveness of tumor cell lines with overexpression of the chemokine receptors CXCR4 and CXCR7, and AXL knock-down in these cell lines significantly hampered tumor cell invasion." (PMID 25193853, 2014). "In colorectal cancer, AXL was found to be overexpressed in liver and peritoneal metastatic tumors and was a prognostic biomarker of poor overall survival in patients with early‐stage colorectal cancer." (PMID 36409270, 2023). "To date, this is the first time that AXL T343M has been reported in colorectal cancer." (PMID 33570712, 2021). "The inhibitor BGB324 of AXL was used to further detect whether XIST enhances the activities of colorectal cancer by AXL signaling." (PMID 32061057, 2020).